FDX1 (ferredoxin 1)
Diseases named in the same sentence as FDX1 in open-access papers (continued):
Sharing a sentence is not in itself a finding about the gene and the disease.
tumor (continued). "Overall, lower expression of FDX1 was associated with worse OS and PFS, especially in ccRCC, and may function as a tumor suppressor due to being downregulated in tumor cells." (PMID 36536785, 2022). "Multiple established immunotherapy cohorts suggested that FDX1 may be a potential predictor of treatment effects for tumor patients." (PMID 36605188, 2022). "Therefore, a large-scale pan-cancer analysis of FDX1 is necessary to explore the therapeutic potential of strategies targeting cuproptosis for tumor treatment." (PMID 36226187, 2022). "Also, we found that the single-cell RNA-seq results in the GSE159115 database demonstrated that the expression of FDX1 was lower in ccRCC tumor epithelial cells than proximal tubule cells, and the bulk-RNA seq in this study also identified this result." (PMID 36536785, 2022). "In addition, ccRCC patients with a lower FDX1 gene expression have a shorter survival time, probably due to the survival advantage of these tumor cells by resisting copper-induced toxicity." (PMID 36225932, 2022). "FDX1 expression and levels of immune cell infiltration in each cancer type were correlated to assess whether this pathway affects the tumor’s immune microenvironment." (PMID 36061184, 2022). "Also, in ccRCC, the tumor tissues showed a marked reduction in FDX1 expression level." (PMID 41198664, 2025). "Furthermore, elevated nuclear FOXO3 levels may suppress the transcription of critical cuproptosis-related genes, such as FDX1, thereby impairing copper-induced cell death and fostering chemotherapy resistance in tumor cells." (PMID 40406488, 2025). "Impairment of FDX1 may further exacerbate this dysfunction, thereby promoting tumor cell death." (PMID 40406488, 2025). "Therefore, our results suggest that FDX1 acts as a tumor suppressor in ccRCC." (PMID 40118855, 2025). "Notably, FDX1 overexpression significantly reduced tumor growth and tumor weight." (PMID 38802900, 2024). "Since FDX1 was a representative gene for cuproptosis, we labeled FDX1-positive or VEGFA-positive tumor/epithelial cells here in the hope of exploring the relationship between cuproptosis and angiogenesis-associated tumor/epithelial cells in intercellular communication." (PMID 38200479, 2024). "Therefore, FDX1 is expected to be a tumor biomarker and potential therapeutic target." (PMID 37313458, 2023). "Furthermore, we found that the expression of FDX1 in adjacent tumor specimens was significantly higher than that in tumors after performing qRT-PCR in our independent clinical database (NBUNH), regardless of whether it was a pair or discrete." (PMID 37432054, 2023). "Hence, we investigated the correlation between the infiltration level of different endothelial and immune cells and FDX1 expression in multiple tumor types from TCGA using the CIBERSORT, CIBERSORT-ABS, TIMER, TIDE, XCELL, QUANTISEQ, MCPCOUNTER and EPIC algorithms." (PMID 37193786, 2023). "Recently, researchers have found that excessive copper concentrations could induce cell death by targeting lipoylated TCA cycle proteins, which showed that the abundance of lipoylated proteins and FDX1 was significantly related to tumor vulnerability to treatment." (PMID 36766692, 2023). "Additionally, we focused on investigating FDX1 as the primary subject of our investigation, examining its expression, prognosis, tumor immune microenvironment, substance metabolism pathway, immune cell infiltration, immunotherapy and chemotherapy drug sensitivity in GBM." (PMID 38114959, 2023). "Furthermore, the FDX1 gene may be a potential prognostic biomarker for tumor diagnosis and assessment." (PMID 37193786, 2023). "Moreover, we explored the tumor‐promoting mechanism of FDX1 in U251 and A172 cells." (PMID 37515314, 2023). "This may be another important factor that FDX1 inhibits tumor invasion." (PMID 36173462, 2023).
tumor (continued). "First, from the aspect of expression levels and copy number variation, we speculated that PDHB, FDX1, and DLD were significantly differentially expressed in BLCA with diagnostic efficacy because the AUCs of them were more than 0.7 to differentiate tumor and normal tissue." (PMID 36506302, 2022). "Hence, FDX1, DLD, DLAT, and CDKN2A may play important roles in immune interactions and may be associated with tumor immune evasion." (PMID 36531222, 2022). "We may deduce the “anti-tumor” effect of FDX1 in those tumors." (PMID 36226187, 2022). "Together, all these findings highlight that resistance to cuproptosis under the miR-21-5p/FDX1 axis, as well as its educated tumor microenvironment is a potential mechanism driving ccRCC progression, and recovery of cuproptosis may be an alternative strategy to overcome this type of disease." (PMID 36611966, 2022). "Therefore, FDX1 may be involved in metabolic dysregulation in carcinogenesis, which could change the phenotype and tumour microenvironment." (PMID 36186457, 2022). "In line with this, IHC staining of ccRCC tissue micro-array (27/62 cRCC with paired adjacent kidney tissues) also confirmed the decreased expression of FDX1 in ccRCC (n = 27), suggesting that FDX1 may serve as a tumor-suppressive regulator in ccRCC development." (PMID 36611966, 2022). "Paired comparisons further confirmed the upregulation of FDX1, DLAT, PDHA1, GLS, and CDKN2A in tumor samples." (PMID 40410601, 2025). "Molecular analysis of tumour tissues revealed that the combination group exhibited significantly reduced protein levels of p‐AKT and GSS, accompanied by decreased FDX1 and increased HSP70." (PMID 41431124, 2025). "Firstly, Western blot analysis revealed that compared to the Vector+PBS + PBS group, the RPS27-RPS24 + PBS + PBS group of mice showed a significant increase in the expression levels of RPS27-RPS24, GLS, FDX1, LIAS, and Lipoy-DLAT proteins in tumor tissues." (PMID 40280903, 2025). "The dual‐targeting MIL‐Cu1.8S‐TPP/FA nanoplatform effectively delivered copper ions to mitochondria and iron ions to tumor cells, modulating key ferroptosis‐ and cuproptosis‐related markers, such as GPX4, GSH, FDX‐1, and HSP70." (PMID 40558386, 2025). "Consistent with prior studies investigating metabolic reprogramming in cancer, we observed significant upregulation of key cuproptosis-related genes, including FDX1, GLS, and CDKN2A, in tumor tissues compared to normal counterparts." (PMID 40410601, 2025). "In the GPL570 dataset, upregulation of LIPT1, FDX1, LIAS, DLAT, DLD, and PDHB was noted in tumor samples, while MTF1 was downregulated." (PMID 40410601, 2025). "Elevated levels of genes like DLAT, FDX1, and PDHA1 correlate with poor outcomes, greater tumor aggressiveness, and immune suppression." (PMID 39867656, 2024). "Therefore, FDX1 could be an important target for tumor immunotherapy." (PMID 39482784, 2024). "To assess the impact of FDX1 on the tumorigenic potential of LUAD cells in vivo, we established a subcutaneous transplantation tumor model using FDX1- overexpressing A549 cells in nude mice." (PMID 38802900, 2024). "After cellular uptake, the ES@CuO microspheres resulted in the downregulation of FDX1 expression and the accumulation of aggregated DLAT, triggering tumor cell cuproptosis." (PMID 38430531, 2024). "Of note, seven out of ten pivotal CRGs, which were identified in Science article, showed significantly altered expression patterns, with CDKN2A exhibited higher and DLAT, DLD, FDX1, LIAS, MTF1, PDHB exhibited lower expression in tumor tissues (P<0.05)." (PMID 37384293, 2023). "Difference analyses showed that 7 of 10 CRGs were dys-regulated in tumor samples compared with those in normal samples, among which LIPT1, PDHA1, GLS and CDKN2A were up-regulated, and FDX1, DLD and MTF1 were down-regulated." (PMID 37333810, 2023). "In tumor tissues, the abundance of CDKN2A and MTF1 were higher, as well as the levels of DLD, FDX1, GLS, LIPT1 and PDHB were down-regulated." (PMID 37662947, 2023).
tumor (continued). "Other genes such as LIPT1, FDX1, and SLC31A1 also play important roles in tumor growth and patient prognosis." (PMID 37239150, 2023). "In this analysis, we found that the expression of FDX1, GLS, and CDKN2A increased when the tumor progressed from the T2 stage to the T3 stage." (PMID 37711156, 2023). "The expression of FDX1 in single cell of COAD and its relationship with tumor functional status were analyzed via CancerSEA database." (PMID 36173462, 2023). "A significant difference in FDX1 expression occurred in different cancer stages, patient race, patient sex, patient age, KIRC subtypes, tumor grade and nodal metastasis status of KIRC." (PMID 37193786, 2023). "The FDX1 staining in tumor sections showed higher in METTL16-WT and -K229E groups than METTL16-K229R group in tumor xenografts." (PMID 37863889, 2023). "We found that genetic mutation and deletion in FDX1 might decrease the level of MHC class I (MHC_I) so that it fails to efficiently bind peptides to MHC molecules and presents the endogenous antigen to CD8+ T cells, causing cytotoxic T lymphocytes to fail to recognize and kill tumor cells." (PMID 37298135, 2023). "The results revealed that LIAS, DLAT, PDHA1, and CDKN2A were significantly upregulated in LUAD tumors compared to normal tissues, while ATP7B, SLC31A1, FDX1, MTF1, and GLS were significantly downregulated in tumor tissues." (PMID 36983664, 2023). "In epithelial cells, FDX1 and DLD were highly expressed in all kinds of cells, and CDKN2A was mainly expressed in tumor." (PMID 37239416, 2023). "Nine CRGs were differentially expressed between tumor and normal tissues, among which NFE2L2, SLC31A1, FDX1, DLD, DLAT, and DLST were lowly expressed in tumor tissues, and ATP7B, CDKN2A, and GCSH were highly expressed in tumor tissues (p<0.05)." (PMID 37205181, 2023). "Apart from copper and SLC31A1, other cuproptosis-related genes, such as FDX1, ATP7B, and lipoyltransferase-1, are also involved in tumor development." (PMID 37313458, 2023). "Among them, the expression levels of CDKN2A, GLS and LIPT1 were significantly upregulated whereas the expression levels of DLAT, DLD, FDX1, MTF1 was significantly downregulated in tumor samples." (PMID 37072493, 2023). "By modulating different substance metabolism,FDX1,LIAS and DLAT, exert impact on tumor cell proliferation, migration, angiogenesis, immune arrest.Specifically,FDX1regulates steroid synthesis." (PMID 36925927, 2023). "Deletion of FDX1 blocks the progress of the TCA cycle, triggering the accumulation of pyruvate and α-ketoglutarate in cells and promotes tumor development." (PMID 37608927, 2023). "We found that FDX1, DLD, PDHA1, MTF1, GLS, and CDKN2A showed differential expression levels between normal and tumor tissues." (PMID 37711156, 2023). "The high-FDX1 expression group had higher ESTIMATE, stromal, and immune scores; however, the distribution of tumor purity demonstrated an opposite trend (p< 0.001)." (PMID 37301546, 2023). "Low levels of FDX1 and PDHA1 expression were observed in tumor tissues that had high levels of CD8 infiltration." (PMID 36895378, 2023). "ATP7B, CDKN2A, FDX1, and SLC31A1 had the lowest expression in tumor cell-enriched region (PanCK-expressing)." (PMID 36618352, 2022). "Therefore, targeting FDX1 may become an alternative strategy for tumor therapy." (PMID 36225932, 2022). "In tumor cell-enriched region, the expression of COPS5, DLAT, DLD, FDX1, NFE2L2, PDHA1 and PDHB in the high score group is higher than that in the low score group, while the opposite is true for DLST, GCSH and LIPT2 (P <0.05)." (PMID 36618352, 2022). "Our analyses of the TCGA cohort of ccRCC showed that higher FDX1 expression is significantly associated with longer OS and PFS, and moreover, its downregulation occurs in ccRCC, which collectively indicates that cuproptosis may act as tumor suppressor in this cancer type." (PMID 36131921, 2022).
tumor (continued). "FDX1 was lower in HNSC, KIRC, KIRP, PCPG, and READ but was higher expressed in other 21 tumor types." (PMID 36210836, 2022). "We found that LIAS and CDKN2A were significantly upregulated in tumor samples, and FDX1, DLD, DLAT, PDHA1, PDHB, MTF1, and GLS were significantly downregulated in tumor samples." (PMID 36531222, 2022). "The gene expressions of AOC1 (P < 0.001), FDX1 (P = 0.003), MT-CO1 (P < 0.001), and ACO1 (P < 0.001) in HCC tumor tissues were remarkably lower than those in normal tissues." (PMID 36313717, 2022). "It was worth mentioning that five of them were downregulated in tumor samples, including DLAT, MTF1, PDZD4, FDX1, and RPS25, and the rest of the genes were all upregulated." (PMID 36010978, 2022). "In the survival analysis, at the 50% cutoff of FDX1, there was a statistically significant difference in OS for LGG, LAML, and KIRC tumor types and in PFS for LGG, ACC, MESO, KIRC, and THCA." (PMID 36605188, 2022). "Also, as for the FDX1 high expression group, some new treatment strategies, such as drug delivery systems in combination with elesclomol, may have had a better performance in tumor treatment." (PMID 36536785, 2022). "Among them, 7 genes (DLAT, DLD, GCSH, LIAS, LIPT1, PDHA1, and PDHB) were upmodulated, whereas 3 genes (ATP7B, FDX1, and SLC31A1) were downmodulated in the tumor group in contrast with the normal group (p < 0.05)." (PMID 36046242, 2022). "qRT−PCR results on CCA samples showed that FDX1, DBT were significantly downregulated in tumor tissue samples, while ATP7A was significantly upregulated." (PMID 36568224, 2022). "The expression level of FDX1 was further identified by the GEO database in the GSE53757 and GSE66271 databases, which contained 72 and 13 paired tumor tissues and adjacent normal tissues, respectively." (PMID 36536785, 2022). "Firstly, the function of FDX1 under cuproptosis inducers was only verified in KIRC cells; more investigations involving other tumor types are essential." (PMID 36605188, 2022). "Apart from the critical regulator FDX1, which was down-regulated in HCC, all other regulators were up-regulated in tumor tissue in comparison with controls." (PMID 36248857, 2022). "A heatmap showed that the levels of expression of ATP7B, DLAT, DLD, LIAS, and SLC31A1 were upregulated and the levels of expression of DBT, FDX1, and PDHB downregulated in tumor samples." (PMID 36092880, 2022). "Of the six cuprotosis-related genes, we found that FDX1, LIAS, DLAT, MTF1, and GLS were differentially expressed between tumor and normal tissue and were upregulated in normal tissue." (PMID 36247012, 2022). "Except FDX1 was significantly downregulated, the other nine genes were elevated in HCC tumor tissues compared to adjacent samples." (PMID 36177029, 2022). "Of the six cuprotosis-related genes included in the signature, we found FDX1, LIAS, DLAT, MTF1, and GLS to be differentially expressed between tumor and normal tissues at the protein level." (PMID 36247012, 2022). "The other main expression differences of FDX1 were in THCA (p = 2.06E–21), BRCA (p = 3.78E–20), KIRP (p = 1.71E–18), and LUAD (p = 2.44E–10), with downregulated expression in human tumour tissue." (PMID 36186457, 2022). "CDKN2A, GLS, LIPT1, and PDHA1 were up-regulated in tumor samples, and FDX1, DLD, MTF1 were down-regulated in tumor samples." (PMID 36176287, 2022). "Similarly, key molecules of cuproptosis, such as FDX1 and DLAT, have been shown to function as tumor suppressors in GI tumors like HCC, and activating this pathway can significantly reduce tumor cell viability." (PMID 41201667, 2025). "Overexpression of GSS significantly attenuated ES–Cu‐induced cell death, reversed the protein‐level changes in FDX1 and HSP70, and enhanced cancer cell proliferation, migration and invasion, indicating that GSS promotes tumour progression primarily by suppressing cuproptosis." (PMID 41431124, 2025).
tumor (continued). "FDX1 expression also correlated with the amount of immune cell infiltration in TEM, especially with the number of macrophages and myeloid-derived suppressor cells, which are known to contribute to immunosuppression of TEM and promotion of tumor growth." (PMID 39062119, 2024). "Furthermore, the Cu+ concentration in tumor cells, generated by the reaction of Cu2+ with GSH, significantly increased, thus inhibiting the expressions of FDX1 and LIAS, triggering DLAT aggregation, and inducing cuproptosis in return." (PMID 38582500, 2024). "We observed that Fdx1+/- +/- were not prone to spontaneous tumors, which is different from tumor-prone Fdxr+/- +/-." (PMID 38251655, 2024). "Additionally, the protein synthesis inhibitor anisomycin also was found to induce cuproptosis in tumor cells, likely via inhibiting Yin Yang 1 (YY1)-mediated transcriptional activation of the key genes in the LA pathway (i.e., FDX1, DLD, DLAT, and PDHB)." (PMID 38918694, 2024). "In addition, we immunohistochemically validated the expression of NRP1, CXCR4, LGR6, CTLA4 and the key regulator of cuproptosis, ferredoxin 1 (FDX1), in nine paired tumor tissues and adjacent tissues." (PMID 37036489, 2023). "FDX1 expression was increased in cases with tumor recurrence, advanced grade, wild type IDH, 1p19q non-codeletion, and history of chemotherapy administration (p <0.05)." (PMID 37301546, 2023). "In addition, we obtained results showed that the remaining CRGs, except FDX1 and MIF1, were significantly highly expressed in tumor tissues." (PMID 37745297, 2023). "The levels of FDX1 expression correlated positively with tumor recurrence, advanced grade, wild type IDH, 1p19q non-codeletion, and chemotherapy status." (PMID 37301546, 2023). "FDX1 was mainly expressed in the proximal and distal tubules of normal renal tissues but not in tumor tissues." (PMID 37432054, 2023). "According to our model, we found that FDX1 was not only an independent prognostic factor of KIRC, but also can regulate the status of immune cells and the expression of immune checkpoints in the tumor microenvironment (TME)." (PMID 36755576, 2023). "After methylation, FDX1 is transcribed into a protein and expressed in normal tissues rather than in tumor samples." (PMID 37432054, 2023). "Analysis of signatures of immunotherapy prediction including immune checkpoints, tumor stemness, HRD, and TMB also indicated FDX1 could be a potential predictor of immunotherapy in multiple tumor types, especially in LGG." (PMID 36825202, 2023). "Correlations were observed between FDX1 expression and B cell, CD4+T cell, CD8+T cell, neutrophil, macrophage, and dendritic cell (DC) infiltration in multiple cancers, suggesting a potential role in the tumor immune microenvironment." (PMID 36825202, 2023). "In Zhang C’s study, they also found that FDX1 was low expressed in tumor tissues of KIRC, and speculated that FDX1might play a role in KIRC as a tumor suppressor gene." (PMID 36755576, 2023). "Besides, our results exhibited that FDX1 was closely related to TMB, MSI, DNMT, and MMR across multiple tumor types." (PMID 36825202, 2023). "Following that, we collected data from the Tumor Immune Estimation Resource (TIMER) and the Gene Expression Profiling Interactive Analysis (GEPIA) databases to examine the link between FDX1 gene expression and immune cell infiltration and the associated gene marker sets." (PMID 36225932, 2022). "FDX1 and DBT are important cuproptosis regulators that can induce cell death through copper ions, and may be a new method of tumor therapy." (PMID 36338990, 2022). "The expression level of FDX1 mRNA in adjacent nontumor tissues was significantly higher than that in tumor tissues." (PMID 36105937, 2022). "Zhang Z found that knocking out the FDX1 gene in lung adenocarcinoma did not result in apoptosis, aberrant cell cycle distribution, or inhibition of tumor cell proliferation." (PMID 36225932, 2022).